IL1B (interleukin 1 beta)
Diseases named in the same sentence as IL1B in open-access papers (continued):
Sharing a sentence is not in itself a finding about the gene and the disease.
psoriasis (continued). "Platelets, which are often elevated during infectious and inflammatory diseases, store a number of inflammatory cytokines and chemokines that play crucial roles in psoriasis, such as IL-1β and CXCL8." (PMID 34565327, 2021). "In this line, it becomes clear that the reduction or inhibition of key cytokines in the pathogenic mechanism of psoriasis (NF-κB, TNF-α, IL-1β, IL-23, and IL-17) plays an important role in the activity of the flavones." (PMID 34943117, 2021). "Previous studies showed that IL-1β is involved in the pathogenesis of psoriasis and psoriatic arthritis." (PMID 34421919, 2021). "Interleukin-1beta (IL-1β) is a pro-inflammatory cytokine also known to be upregulated and to play a role in psoriasis, as well as to regulate immune function." (PMID 34445455, 2021). "Most of these targets exhibited abnormal expression and were designated as the therapeutic targets in psoriasis, such as the cytokines and chemokines (IL-1β, IL-6, TNF, IFN-γ, CXCL8, CCL2)." (PMID 34168554, 2021). "In cultured keratinocytes, AIM2 and cytosolic DNA triggered the release of IL-1β, therefore indicating that cytosolic DNA can trigger AIM2 inflammasome and IL-1β activation in psoriasis." (PMID 34502368, 2021). "A previous study showed that DCs in IMQ-treated skin mainly produce IL-1β; the study also showed that the IL-1β–IL-1R signaling pathway contributes to skin inflammation and psoriasis pathogenesis." (PMID 34421919, 2021). "The pro-inflammatory cytokines, such as IL-6, TNF-α, IL-1β, IL-22, and IL-17A, have been reported to be up-regulated in psoriatic lesioned tissue and serum, and these cytokines likely drive the psoriasis pathogenesis." (PMID 33323018, 2021). "We would encourage researchers to examine the diagnostic and prognostic role of IL1-β, TNF-α, IL-2 and IFN-γ in different psoriasis clinical forms." (PMID 34209865, 2021). "After activation, AIM2 assembles inflammasome, driving IL-1β secretion and contributing to psoriasis." (PMID 33681365, 2021). "The study shows that patients with psoriasis have increased plasma levels of IL-1β and IL-18 and increased constitutive expression of the inflammasome sensors NLRP3, NLRP1, and AIM2 in peripheral blood cells, together with increased caspase 1 reactivity." (PMID 34502368, 2021). "A recent study had shown that metformin prevented and treated psoriasis by inhibiting IL-1β targeting AMPK in keratinocytes." (PMID 34512732, 2021). "Chloroquine or TCDD treatment of psoriasis skin biopsies enhanced the production of the proinflammatory cytokines, IL-1β, IL-6, and TNF-α compared to chloroquine- or TCDD- treated controls." (PMID 32235789, 2020). "In psoriasis skin biopsies, the synthesis of proinflammatory cytokines, including IL-1β, IL-6, and TNF-α, was significantly enhanced by TCDD and chloroquine, compared to controls." (PMID 32235789, 2020). "In psoriasis patients, a high presence of inflammatory dendritic cells that through IL-1β and IL-23 production can polarize Th17 cells towards a pathogenic phenotype has also been described (IL-17 and IFN-γ production)." (PMID 32801996, 2020). "Intriguingly, IL-1β expression is higher in psoriatic lesions than in healthy skin, and decreases in parallel with clinical improvement of psoriasis severity." (PMID 32917058, 2020). "Owing to its critical role in eliciting innate immune responses, IL-1β has been suggested to contribute to various skin diseases, including psoriasis, vitiligo, systemic lupus erythematosus (SLE), and atopic dermatitis (AD)." (PMID 32528469, 2020). "T cells and DC infiltrate the epidermis migrating into all layers of the epidermis and as a consequence levels of the pro-inflammatory cytokines IFN-α, IFN-γ, TNF-α, IL-1β, IL-23, and IL-17 are high in psoriasis lesions." (PMID 32708987, 2020). "Recently, the IL-1β-IL-1R signalling pathway controlled by NLPR3 inflammasome has been reported to play a critical role in the pathogenesis of psoriasis in humans and induced by IMQ in mice." (PMID 32194991, 2020).
psoriasis (continued). "IL-1β, together with IL-23, is involved in Th17 differentiation and the production of IL-17 and IL-22, which are crucial in the pathogenesis of psoriasis." (PMID 33149756, 2020). "We identified the pro-inflammatory cytokines IL17, INFγ and IL1β as important inducers of miR-155 in KCs, all factors well-known to contribute to the pathogenesis of psoriasis." (PMID 33291448, 2020). "AIM2 recognizes cytosolic DNA and triggers inflammasome activation and IL-1β production in keratinocytes, thereby contributing to psoriasis pathogenesis." (PMID 33055429, 2020). "The key role of TNF-α and IL-1β as cytokines involved in the pathogenesis of psoriasis is well known." (PMID 32708987, 2020). "CXCL8 is regulated by other cytokines such as IL17A and IL1B, which is critical for the pathogenesis of psoriasis and influences lesional keratinocytes of psoriasis." (PMID 32785106, 2020). "IL1B is a key factor in cutaneous inflammation and plays an axial role in the instigation of an inflammatory Th17 micro-milieu in psoriasis and other autoinflammatory diseases." (PMID 32785106, 2020). "Cytosolic DNA triggers the activation of the AIM2 inflammasome and IL-1β in psoriasis; LL-37 blocks AIM2 inflammasome activation." (PMID 32528469, 2020). "Patients with active psoriasis had significantly higher salivary IL1β, TNF-α, TGF-β, and MCP-1 levels than healthy controls." (PMID 32046271, 2020). "In the epidermis of skin lesions of psoriasis patients, IL-1β has been shown to be increased and effective treatment of psoriasis led to a significant decrease in epidermal IL-1β expression." (PMID 32194991, 2020). "To test this possibility, we performed co-culture of macrophages with NETs, and measured mRNA expression levels of TNF-α, IL-1β, and IL-36γ, which are involved in the pathological condition of psoriasis." (PMID 33214582, 2020). "Blocking of the TNF-α, the NF-κB pathways have been a focus of the anti-psoriasis treatments as it leads to the reduction in the inflammasome activation and downregulation of the cytokine such as IL-1β." (PMID 31680964, 2019). "Langerhans cells from active lesions expressed psoriasis-associated genes (IL23, IL1B, IL15) and showed increased IL-23 production after ex vivo stimulation." (PMID 31673756, 2019). "Secondly, IL-1β is another vital pro-inflammatory cytokine that promotes psoriasis and metabolic syndromes potential via the activation of keratinocytes and the inflammation-induced destruction of pancreatic β-cells, respectively." (PMID 31521168, 2019). "Since IL-1β is a well-known initiator and effector for inflammation, several proteins involved in the production of this interleukin in psoriasis were investigated." (PMID 30744173, 2019). "We observed that CAV-1-reduced monocytes exacerbated the production of psoriasis-related inflammatory cytokines (IL-1β and IL-6)." (PMID 30644419, 2019). "The psoriasis-associated supersets were also found to be closely linked in the blood network via KDs such as CTSH, IL1B, STAT1, and IFITM2." (PMID 30642337, 2019). "A number of evidence links IL-1β and Th17 pathways in psoriasis pathogenesis both in mice and in humans." (PMID 30034395, 2018). "Recently, substantial studies have identified a central role of pro-inflammatory cytokines, including tumor necrosis factor α (TNF-α), interleukin (IL)-1β, IL-6, IL-23, and IL-17, in psoriasis pathogenesis." (PMID 29619028, 2018). "Among ILC subsets expressing NKp44 are the ILC3, which express the transcription factor RORγt and upon stimulation with IL-1β and IL-23 produce both IL-17 and IL-22 and are thought to be involved in the pathogenesis of psoriasis." (PMID 29316717, 2018). "Consistent with this possibility, expression responses to IL-1B and IL-36 in epidermal KCs were correlated with those in lesional psoriasis skin." (PMID 29434599, 2018). "The authors found that, at baseline, mean IL-1β levels were higher in patients with psoriasis than in controls." (PMID 29619128, 2018).
psoriasis (continued). "We identify IL-1B- and IL-36-responsive genes, characterize known functions of such genes, and investigate relationships to psoriasis (PsV and GPP) based upon skin lesion transcriptome signatures." (PMID 29434599, 2018). "An association between psoriasis and chronic PDIS has been shown, and increased concentrations of proinflammatory cytokines such as TNF-α and IL-1β have been found in saliva from patients with psoriasis." (PMID 28748036, 2017). "To confirm these results in vivo, we further blocked CCN1 with a monoclonal antibody or a lentiviral vector expressing shRNA in IMQ-/IL-23-induced psoriasis-like mice and found impaired IL-1β expression following CCN1 silencing." (PMID 28266627, 2017). "In psoriasis, interleukin-1β (IL-1β) is an important player for the development of the inflammatory Th17 phenotype." (PMID 28422993, 2017). "The role of TNF-α, IL-17 and IL-1β in psoriasis pathogenesis has been well documented, being a particularly effective strategy to block their production." (PMID 29295585, 2017). "Together, this study identified disease-intrinsic regulators, triggers and therapeutic mechanisms of caspase-5 dependent epidermal IL-1β production in psoriasis." (PMID 28422993, 2017). "Systemic interference with IL-1β shows beneficial effects in clinical trials with patients suffering from psoriasis, specifically in the inflammatory manifestations of psoriasis." (PMID 28422993, 2017). "Regarding the relevance of IL-17A in psoriasis, we investigated the caspase- mediated IL-1β activation by epidermal keratinocytes further." (PMID 28422993, 2017). "Here, our data indicate that vitamin D further acts as a direct suppressor of caspase-5 and IL-1β production in keratinocytes suggesting a novel anti-inflammatory mechanism relevant in psoriasis and other Th17-driven inflammatory skin diseases." (PMID 28422993, 2017). "IL-1β is a potent player in cutaneous inflammation and central for the development of a Th17 micro-milieu in autoinflammatory diseases including psoriasis." (PMID 28422993, 2017). "Many cytokines, including interleukin-23(IL-23), IL-17A, TNF-α, IL-6, IL-1β and IL-22, are also involved in the pathogenesis of psoriasis." (PMID 26007179, 2015). "This trend appears to agree well with transcriptome studies, which have also shown that genes differentially expressed in psoriasis lesions include a disproportionate number of IL-1B targets." (PMID 26251673, 2015). "IL-17 elicits its pro-inflammatory effects in RHE, stimulating the expression of several genes including IL23A, IL1β, and IL36B (IL1F8) that have been implicated in psoriasis pathogenesis and found to be over-expressed in psoriatic lesional skin." (PMID 24587313, 2014). "The inflammatory response in psoriasis is characterized by production of TNFα and production of IL1β." (PMID 24069534, 2013). "In fact, these results demonstrate that in healthy conditions, insulin is able to regulate cell proliferation and differentiation of keratinocytes with protein kinases, PI3-K protein and kinase B. In psoriasis, IL-1β is found in large quantities in the dermis." (PMID 23935446, 2013). "Inflammasome proteins are synthesized by keratinocytes, activated in psoriasis model and IL-1β is released from cells in response to the injury and metabolic stress." (PMID 23967056, 2013). "It is on that basis, we discovered that curcumin can suppress inflammation in IMQ-induced psoriasis-like mice model and decrease the cytokines production, such as IL-17A, IL-17F, IL-22, IL-1β and TNF-α." (PMID 23825622, 2013). "When activated in the epidermis in mice, PPAR β/δ also induces the complete IL-1 signalling “module” characteristic of psoriasis including pro-inflammatory (IL1β, IL1F8), as well as anti-inflammatory cytokines (IL-1F5, IL1RA)." (PMID 22606335, 2012).
psoriasis (continued). "Stimulation with both TNF-α and IL-1β induced migration to CCL19 in both healthy individuals and patients with psoriasis (P < 0.05), with the effect being more pronounced in IL-1β-stimulated samples." (PMID 21933242, 2012). "This dual-phase regulation may explain the clinical observation of psoriasis patients developing type 2 diabetes, as persistently elevated IL-1β levels are characteristic of psoriatic inflammation." (PMID 41508030, 2026). "Consequently, exploring IL-1β-targeting therapeutics agents and their downstream regulatory pathways holds significant importance for developing advanced psoriasis management strategies." (PMID 41508030, 2026). "Therefore, this study validates the therapeutic efficacy of brusatol for psoriasis using murine models and HaCaT keratinocyte cells, employing proteomics and lipidomics to identify IL-1β as a key target." (PMID 41508030, 2026). "The application of NF-κB antagonists can significantly reduce epidermal thickness, acanthosis, and inflammatory symptoms in psoriasis-like mice.Activation of the NF-κB signaling pathway induces the expression of pro-inflammatory factors such as NO, IL-1β, IL-6, and COX-2." (PMID 40333872, 2025). "Corroborating the notion, therapies targeting pyroptosis, such as IL-1β inhibitors, have shown moderate success in psoriasis, but the same treatments have had limited efficacy in HS, likely due to differences in the tissue-specific manifestation of inflammation." (PMID 41007405, 2025). "In psoriasis, curcumin exhibits its anti-inflammatory effects by reducing the expression of cytokines such as interleukin-17A (IL-17A), interleukin-17F (IL-17F), interleukin-22 (IL-22), IL-6, IL-1β, and TNF-α, and by inhibiting NF-κB activation." (PMID 40718452, 2025). "Moreover, the therapeutic potential of modulating inflammasome pathways has gained traction, with several studies exploring NLRP3 inhibitors or IL-1β blockade in preclinical models of psoriasis and other chronic inflammatory diseases." (PMID 40771724, 2025). "Previous studies have indicated that pyroptosis in psoriasis triggers caspase-1 activation, increases IL-1β and IL-18 expression, and activates the IL-23/Th17 pathway, leading to the secretion of large amounts of inflammatory cytokines and chemokines, which ultimately induces skin inflammation." (PMID 40722833, 2025). "IL-1β, NLRC4, MEFV, and CASP have been reported as inflammasomes associated with psoriasis." (PMID 40861543, 2025). "Similar to ACD, psoriasis is caused primarily by TNF-α, IL-1β, and IL-6 produced by keratinocytes, which stimulate plasmacytoid dendritic cells to produce interferon-α (IFN-α) followed by its stimulation of IL-12 and IL-23 release by dendritic cells nearby lymph nodes." (PMID 41226679, 2025). "Additionally, IMQ stimulates the release of inflammatory factors such as IL-1β, IL-6, IL-23, and IL-17 leading to produce psoriasis-like symptoms in the skin, including erythema, scaling, and epidermal thickening." (PMID 40072672, 2025). "The development of psoriasis is significantly influenced by the IL-23/Th17 axis and IL-1b." (PMID 38712377, 2025). "IL-1β signaling is well-known to be involved in the development of psoriasis." (PMID 40343299, 2025). "While IFNγ and the IL‐17/IL‐23 axis are well established in psoriasis, IL‐4 has been shown to downregulate IL‐1β and IL‐6 production by psoriatic cells and may aid in psoriasis resolution, as observed during treatment with vitamin D3 analogues." (PMID 40926620, 2025). "Elevated TNF-α, IL-1β, and IL-6 levels in psoriasis reduce triglyceride clearance." (PMID 38683749, 2024). "Moreover, IL-1β synergizes with IL-23 to activate IL-17 A-producing γδ T cells, a major contributor to psoriasis, and the IL-1β–IL-1R1 signalling pathway plays a crucial role in the pathogenesis of psoriasis." (PMID 38704587, 2024).
psoriasis (continued). "Furthermore, α-humulene and torilin from Cnidi fructus were identified as targeting psoriasis-related proteins, including IL1B, TNF, NOS2, and NFKBIA." (PMID 39590306, 2024). "Moreover, IL-1R1 blockade significantly reduced the population of IL-17 A-producing γδ T cells, CD4+ T cells, and CD8+ T cells, consistent with the role of IL-1β in the development of IL-17 A-producing T cells and psoriasis pathogenesis." (PMID 38704587, 2024). "We found that in the skin of psoriasis-like mice, Il1b and Il6 were mainly expressed in neutrophils, while Il17a was mainly expressed in T cells, Il18 was mainly expressed in macrophages and fibroblasts, and Tnfa was mainly expressed in macrophages and T cells." (PMID 39717896, 2024). "Furthermore, our findings suggest the therapeutic potential of saccharin, a safe disaccharide inhibiting pro-IL-1β expression, for treating psoriasis." (PMID 38704587, 2024). "IL-1β was the most expressed cytokine in HS lesions compared to healthy skin, and its expression was even more pronounced than in other inflammatory skin diseases such as psoriasis." (PMID 39274425, 2024). "Furthermore, both necroptosis and ferroptosis in keratinocytes have been implicated in psoriasis and IMQ-induced psoriasis-like dermatitis, through the release of inflammatory cytokines such as S100A8, S100A9, HMGB1, IL-33, IL-1β, and IL-6." (PMID 38429278, 2024). "Furthermore, the transcriptional signature from affected skin revealed upregulation of key human psoriasis genes, including Lcn2 and Defb4, cytokines Tnf, Il1b, and Il36a/g, and chemokine ligands Ccl2, Cxcl9, and Ccl20." (PMID 38528069, 2024). "In this study, we found that gasdermin D (GSDMD) is higher in human psoriatic skin than that in normal skin, and in imiquimod-induced psoriasis-like mouse skin, the expression of Gsdmd was most significantly altered in neutrophils and Il1b was also mainly expressed in neutrophils." (PMID 39717896, 2024). "Psoriasis is an inflammatory skin disease characterized by the hyperproliferative epidermal keratinocytes and significant immune cells infiltration, leading to cytokines production such as IL-1β, TNF-α, IL-23, and IL-17." (PMID 38704587, 2024). "Furthermore, it has been demonstrated that suppression of miR-31-5p in keratinocytes in psoriasis suppresses NF-κB-driven promoter-luciferase activity and IL-1β, CXCL1, and CXCL5 production." (PMID 39259390, 2024). "We cannot rule out the contribution of other regulatory mechanisms besides IL-1β and CXCL2 to neutrophilia and psoriasis pathogenesis caused by myeloid autophagy deficiency as we assessed the expression of a selected set of cytokines and chemokines central to inflammatory diseases." (PMID 38704587, 2024). "Moreover, IL-1β has been reported to be significantly increased in patients with psoriasis and even more in HS, both on the transcriptional and protein levels." (PMID 38248345, 2024). "IL-1β promotes the differentiation of Th17 cells to secrete IFN-γ, and IL-18 enhances IFN-γ-induced production of C-X-C motif chemokine 9 (CXCL9), CXCL10 and CXCL11, which migrate from dermis to epidermis causing chronic inflammatory activation of psoriasis." (PMID 39689159, 2024). "IL-17, IL-23, and IL-1β are key cytokines that mediate the inflammatory response in psoriasis." (PMID 39109246, 2024). "In this regard, saccharin, which exhibits an autophagy-independent anti-inflammatory effect, could be considered a potential candidate for treating psoriasis involving IL-1β dysregulation." (PMID 38704587, 2024). "To further verify whether SFN could modulate the expression of inflammatory factors and chemokines during psoriasis development, we evaluated the mRNA levels of Il1b, Il6, and Ccl2 using qRT‒PCR." (PMID 38007430, 2023).